WIF1 (Wnt inhibitory factor 1)
Diseases named in the same sentence as WIF1 in open-access papers (continued):
Sharing a sentence is not in itself a finding about the gene and the disease.
tumor (continued). "Hypermethylation of WIF1 gene promoter region silences WIF1 expression by adding methyl groups to CpG islands, impairing its tumor-suppressive function and promoting tumor growth and progression." (PMID 38001653, 2023). "According to miRDB: the microRNA database, miR-181a-5p has 887 target genes, including BCL2, LMO3, PTEN, SNAI2, WIF1, which are related to tumor development, cell cycle control, signal transduction processes, and apoptosis." (PMID 37697308, 2023). "This explains the ODC activity inhibition due to the depletion of polyamine levels in the tumors, thereby decreasing c-myc expression and increasing p21cip1/wif1 expression, leading to tumor growth arrest." (PMID 37568816, 2023). "Elevated methylation intensity of SOSTDC1, DACT2 and WIF1 was observed in patients who had advanced tumour stage, positive nodes and local or distant metastasis." (PMID 34997107, 2022). "Extracellular inhibition of the WNT signaling pathway, WIF1, plays an important role in controlling cell proliferation and acts as a tumor suppressor." (PMID 36012492, 2022). "SOSTDC1 and DACT2 did show prominent differential methylation in DCIS and invasive BC, but methylated WIF1 was significantly increased (P = 0.031) in DCIS tumours." (PMID 34997107, 2022). "Wnt inhibitory factor 1 (WIF1) is a tumor suppressor, which can interact with Wnt protein to inhibit the Wnt pathways." (PMID 35308223, 2022). "Taken together, our findings revealed that SLC16A1-AS1 was a tumor suppressor and inhibited the tumorigenesis and highly aggressive behaviors of BC cells via sponging miR-552-5p to activate WIF1 both in vitro and in vivo." (PMID 35372039, 2022). "WIF1 is a tumor suppressor that reducescell growth in HCC, and its expressionlevel is a prognostic indicator of the course of the disease." (PMID 36714033, 2022). "In support, WIF1 overexpression significantly reduces the motility and invasiveness of PC-3 cells in vitro, and reduces tumor burden in PC-3 xenografts in vivo." (PMID 35204808, 2022). "declared that ALKBH5 also increased the expression of WIF-1 (Wnt inhibitory factor 1) and inhibited the Wnt pathway to suppress these tumor features." (PMID 36686788, 2022). "A significant hypermethylation of NPY and WIF1 in the tumor tissues was demonstrated (p < 0.001 for NPY; p < 0.001 for WIF1)." (PMID 34627187, 2021). "Tanemura at al. demonstrated that during tumor progression, several tumor-related genes and loci, including WIF1, SOCS1, RASSF1A, TFPI2, MINT17, and MINT31, gain methylation with advancing stages." (PMID 34575678, 2021). "Incubation with PDAC cells induces tumor cell apoptosis, as circRNA-0030167 inhibits miRNA-338-5p, thereby increasing the expression of tumor suppressor WIF1." (PMID 34496946, 2021). "Comparing tumor samples and non-tumor colonic tissues, TCGA data were analyzed for WIF1 and NPY transcripts." (PMID 34627187, 2021). "The NPY and WIF1 methylation testing was performed on the 11 pairs of tumor/non-tumor tissue adjacent to the tumor." (PMID 34627187, 2021). "In a preclinical study, ISL was able to shed a novel light on reversing the epigenetic changes of Wnt inhibitory factor 1 (WIF-1), which induced the demethylation of WIF-1 promoter and subsequently prevented tumor initiation by inhibiting CSCs." (PMID 33401375, 2021). "Using the same primer set and PCR condition, we examined the methylation status of the WIF1 promoter in 29 tumor samples from previously untreated MCL patients." (PMID 33477402, 2021). "In this study, blood-derived DNA methylation levels of two tumour-related genes, namely, ZNF331 and WIF1, and their impacts on the risk and prognosis of GC were evaluated." (PMID 33992091, 2021). "Using Crystal Digital PCRTM, the NPY and WIF1 hypermethylation testing was performed on the 23 tumor tissues from CRC patients." (PMID 34627187, 2021). "Aberrant methylation of WIF1 was found in CRC with a statistically significant association with increasing tumor stage and tumor differentiation." (PMID 34277443, 2021).
tumor (continued). "The tumor suppressor role of WIF1 is also supported by the observation that the silencing of WIF1 by methylation and by noncoding RNAs contributes to a large variety of tumors." (PMID 34944004, 2021). "The tumor-promoting function of miR-181a is exerted through repression of its downstream target gene WIF-1 (Wnt inhibitory factor-1), an inhibitor of the Wnt signaling pathway." (PMID 32197476, 2020). "Plasma concentration of ctDNA was controlled by determination of methylated WIF1-promotor ctDNA burden as a second tumor marker for mCRC." (PMID 32766143, 2020). "The expression levelsof WIF1 demonstrated regulatory effects of this tumor suppressorgene on the Wnt signaling pathway and thus, the anti-proliferation effect ofBetatrophin." (PMID 32745158, 2020). "Among others, the expression of several genes such as Axin2, Ptn, Wif1, Clu and Wfdc18 was particularly characteristic for these tumor-specific cell clusters." (PMID 32080185, 2020). "Y = − 0.0159 × p16 − 0.0067 × WIF1 − 0.0162 × TGF-β − 1.2260 × age grade + 1.2205 × gross tumor volume grade + 6.4351." (PMID 31109334, 2019). "The SFRP1, SFRP2, and WIF1 methylation levels in tumor tissues were significantly higher than that in adjacent non-tumor tissues (Mann-Whitney U test, P < 0.001)." (PMID 31830937, 2019). "In this study, we found that the promoter methylation level of SFRP1, SFRP2, and WIF1 was enormously higher in tumor tissues than that in adjacent non-tumor tissues." (PMID 31830937, 2019). "The SFRP1, SFRP2, and WIF1 methylation levels in tumor tissues were significantly higher than that in adjacent non-tumor tissues (P < 0.001)." (PMID 31830937, 2019). "Comparison of expression levels demonstrated higher levels of both Wif1 and Axin2 within APC2-deficient tumours c,d." (PMID 31291912, 2019). "For further survival analysis, the cut-off values of SFRP1, SFRP2, and WIF1 methylation for distinguishing the survival status accounted for 10.0, 50.0, and 50.0% in tumor tissues." (PMID 31830937, 2019). "As far as their biological functions are concerned, low expression level of p16 and WIF1 is observed in pituitary tumorigenesis and is necessary for tumour progression, the methylation of their promoters indicates a poor prognosis." (PMID 31109334, 2019). "Consistently, inhibition of this pathway, for example through restoration of endogenous inhibitors such as WIF-1 and Dkk-3 resulted in tumor regression, increased apoptosis and reduced cell motility both in vitro and in vivo." (PMID 29534536, 2018). "As a common antagonist of Wnt/β-catenin signaling, Wnt inhibitory factor 1 (WIF1) plays an important role in the tumor progression." (PMID 29435185, 2018). "Altogether, data from the literature as well as our data do not exclude the existence of other mechanisms involved in the regulation of Wif1 during the process of tumor initiation and progression." (PMID 30123421, 2018). "In summary, the frequency of WIF-1 hypermethylation significantly increased in NSCLC tumor compare with normal lung tissue." (PMID 27911280, 2017). "Protein expression levels of WIF1 and members of the Wnt family were also measured to assess the potential tumor suppressor role of methylated WIF1 in the Wnt pathway in CS." (PMID 28484252, 2017). "It is required for gene silencing of the HOXD locus by PRC2, which controls the expression of several critical tumor suppressors such as WIF-1, SETD2, and PTEN." (PMID 28938586, 2017). "The percentage of methylated reference (PMR) levels of SFRP1, SFRP2, PRKCB and WIF1 in 111 NSCLC tumor tissues and 111 paired adjacent tissues were quantified by SYBR green-based quantitative methylation-specific PCR (qMSP)." (PMID 28422739, 2017). "We found that the tumor tissue from mice that had been treated with MRx102 had significantly increased WIF1 expression." (PMID 27400883, 2016).
tumor (continued). "EBV miRNAs also target two other tumor-suppressor genes: ebv-miR-BART19-3p targets WIF1 (WNT inhibitory factor 1), while ebv-miR-BART7 and ebv-miR-BART19-3p target APC (adenomatous polyposis coli)." (PMID 27271654, 2016). "Ectopic expression of WIF-1 in NPC cells resulted in significant inhibition of tumor cell colony formation efficiency." (PMID 29147412, 2015). "Meanwhile, over-expression of WIF1 dramatically reduces tumor growth in a xenograft mouse model, accompanied by an increased E-cadherin and CK18 expression and a decreased vimentin level in tumor tissues." (PMID 24618337, 2014). "We also found that knockdown of WIF-1 gene expression by siRNA reversed miR-181a-RNAi-mediated suppression of tumor cell migration." (PMID 24755295, 2014). "For all methylated normal samples, the corresponding DCIS tumour also was methylated for the same gene, apart from one case (sample S25) where the normal tissue showed heterogeneous methylation for WIF1 while the DCIS was unmethylated." (PMID 25331261, 2014). "Our data suggest that up regulation of miR-181a plays an important role in CRC cell metastasis, and that the tumor-promoting function of miR-181a is through repressing its downstream target gene WIF-1." (PMID 24755295, 2014). "Our results also showed that low-level expression of WIF-1 is positively correlated with tumor metastasis and/or poor prognosis." (PMID 24755295, 2014). "In this study, the detection of methylated Wif-1 in stool, urine or serum samples has a higher diagnosis accuracy to detect advanced neoplasia compared to FOBT (0.90 [0.84–0.94] vs. 0.83 [0.77–0.88], p = 0.02)." (PMID 25025467, 2014). "miR-181a has strong tumor-promoting effects through inhibiting the expression of WIF-1, and its potential role in promoting epithelial-mesenchymal transition." (PMID 24755295, 2014). "Our results, along with the roles of WIF-1 in tumor progression, indicate the involvement of the miR-181a-WIF-1 regulation chain in CRC progression." (PMID 24755295, 2014). "Wif-1 appeared to be the most sensitive marker of advanced neoplasia in either urine or serum samples (52% and 29%) compared to ALX-4 and Vimentin (23% and 15% vs. 4% and 8%, respectively)." (PMID 25025467, 2014). "A significant decrease in WIF-1 expression was seen in tumor tissues compared with the matched adjacent normal tissue, while their miR-181a expressions were shown an inverse trend." (PMID 24755295, 2014). "WIF1 functions as a tumor-suppressor gene, and it has been shown to be epigenetically silenced in various cancers." (PMID 24376796, 2013). "As illustrated for WIF1 marker, sequencing results revealed that all CpG covering the amplicon in tumor samples were uniformly methylated." (PMID 24289328, 2013). "For instance, overexpression of WIF-1 significantly decreased tumor growth and markedly reduced the number of lung metastasis of 143B cells in vivo." (PMID 22640921, 2012). "WIF1 functions as a tumor suppressor that inhibits Wnt signaling through direct interaction with Wnt proteins, its activation leading to cell cycle arrest." (PMID 22645611, 2012). "Wnt inhibitory factor-1(WIF-1) acts as a Wnt-antagonists and tumor suppressor, but hypermethylation of WIF-1 gene promoter and low expression activate Wnt signaling aberrantly and induce the development of various human tumors." (PMID 20334650, 2010). "The wet tumor weights were 0.84 ± 0.256 g in the control group and 0.314 ± 0.18 g in the WIF1- transfectants group (n = 13, mean ± SD; P < 0.05, Student's t test)." (PMID 20573255, 2010). "Therefore, up-regulation of this gene can be a promising strategy in controlling tumor proliferation and metastasis and our results indicated that in all three cell lines the level of WIF1 significantly increased after using CC-CUR." (PMID 38365810, 2024). "Finally, expression of two known as tumor suppressor genes, Cav1 (caveolin 1) and Wif1 (wingless-type inhibitory factor-1) was examined." (PMID 37513116, 2023).
tumor (continued). "Furthermore, adiponectin inhibits the Wnt and Akt pathways by increasing Wnt inhibitory factor-1 (WIF1) in MDA-MB-231 cells leading to a tumor-suppressive effect." (PMID 36428526, 2022). "In other words, restoration of WIF1 may be therapeutically useful even in these ‘outlier’ cases, since the WIF1 can mediate tumor suppressor effects via other mechanisms." (PMID 33477402, 2021). "SFRP1, SFRP2, and WIF1 were frequently hypermethylated in CRC tumor tissues." (PMID 31830937, 2019). "The promoter of SFRP1, SFRP2, and WIF1 were frequently hypermethylated in CRC tumor tissues." (PMID 31830937, 2019). "Moreover, in vitro studies have shown that lenti-miR-181a targets Wnt inhibitory factor-1 (WIF-1) and can boost tumor progression, metastasis, and EMT." (PMID 31887997, 2019). "Due to limitation of available tumour samples, qRT-PCR analysis could only be performed on two WNT signalling target genes (Wif1 and Axin2) using RNA from two Apc2-deficient GCTs, with Apc2-proficient ovaries used as control material." (PMID 31291912, 2019). "WIF1 is a tumor suppressor inhibiting tumour angiogenesis through both WNT and VEGF pathways." (PMID 30912746, 2019). "However, immunostaining of Apc tumor sections revealed the heterogeneous expression of both TRα1 and WIF1 proteins." (PMID 30123421, 2018). "In addition, we summarize these findings and discuss the tumor suppressor function, as well as the clinicopathological significance of WIF-1 in NSCLC." (PMID 27911280, 2017). "We further examined the methylation levels of WIF1 in 45 tumor specimens of patients with CS." (PMID 28484252, 2017). "In fact, many studies have reported that WIF-1 down-regulation is involved in tumours, including in HCC, and could trigger the Wnt/β-catenin signal pathway." (PMID 28899352, 2017). "The decrease in tumor formation by MRx102 in the patient-derived xenograft model was WIF1-dependent, demonstrating that MRx102 is a potent inhibitor of the Wnt pathway in low WIF1 expressing NSCLC patient tumors." (PMID 27400883, 2016). "The WIF-1 gene has been reported to have a tumor suppressor role in various cancers." (PMID 26198328, 2015). "High levels of miR-181a in tumor cells correlated with low levels of WIF-1 protein expression." (PMID 24755295, 2014). "The tumor-suppressor gene WIF1 was the most strongly expressed in the PDL." (PMID 24376796, 2013). "Human WIF1 is also epigenetically silenced in many tumors that have heightened Wnt signaling, and addition of exogenous WIF1 to such tumors reduces Wnt signaling, slows tumor growth and increases apoptosis." (PMID 22383891, 2012). "Moreover, WIF1 expression resulted in decreased cell motility and invasiveness in cell cultures, as well as reduced tumor growth in a PCa xenograft model." (PMID 20573255, 2010). "WIF-1 silencing may be an early epigenetically carcinogenic event and plays a role in tumor development and progression." (PMID 20334650, 2010). "However, we did show that WIF1 overexpression significantly inhibits in vivo tumor growth of PC3 cells in a xenograft model." (PMID 20573255, 2010). "Ectopic WIF1 expression attenuated tumor growth by approximately 63%." (PMID 20573255, 2010). "Moreover, WIF1 expression significantly reduced tumor growth by approximately 63% in a xenograft mouse model." (PMID 20573255, 2010). "Quantitative real-time PCR analysis of the same samples as used in the microarray analysis confirmed the marked downregulation of WIF1 in both neoplastic epithelium and tumor stroma and the marked upregulation of GREM1 in both DCIS-associated and IDC-associated stroma." (PMID 19187537, 2009). "The remaining 55 tumor specimens (36.7%) revealed solely unmethylated WIF1 promoter sequence." (PMID 19570204, 2009). "Interestingly, stratifying the data by patient group and adjusting for age showed that the male-associated increased methylation of WIF1 and SFRP1 was specific for the neoplasia-free subjects only." (PMID 18542073, 2008).
tumor (continued). "Moreover, WIF-1 expression levels were observed to decrease in PR group and increase in PD group at therapy-Cycle 6, differing from previous findings of its anti-tumor effects in CC via the Wnt signaling pathway." (PMID 38835778, 2024). "Other examples of tumor suppressor genes described as mutated in OS include the β-catenin regulatory protein APC (Adenomatous polyposis coli), the metalloproteinase inhibitor TIMP3 (Metalloproteinase inhibitor 3) and the Wnt pathway inhibitor WIF-1 (Wnt inhibitory factor 1)." (PMID 35884563, 2022). "Thus, WIF1 is a tumor suppressor gene whose expression should be rather inhibited in tumor tissues." (PMID 34627187, 2021). "Thus, it seems possible that the tumor suppressive effect of WIF1 overexpression on ASZ001 cells may be exerted, at least in part through the inhibition of non-canonical Shh signaling mediated by Ptch2." (PMID 34944004, 2021). "The importance of WIF1 as a Wnt antagonist is illustrated by the fact that transgenic mice in which the WIF1 gene was disrupted were more susceptible to spontaneous and radiation-induced osteosarcoma than wild type animals, suggesting that WIF1 may function as a tumor suppressor." (PMID 34944004, 2021). "Methylation of several tumor-related genes, including MINT17, MINT31, TFPI2, WIF1, RASSF1A, and SOCS1, comprising the first melanoma CIMP, increased significantly with advanced clinical stages, suggesting that their inactivation is associated with tumor progression." (PMID 34944843, 2021). "Therefore, MetctDNA could be a promising surrogate marker for tumor follow-up in patients with CRC, which means that WIF1 and NPY could instead be tumor-specific mutations." (PMID 28903450, 2017). "SCFAs inhibit DNA methyltransferases (e.g., DNMT1), leading to demethylation and re-expression of tumor suppressor genes (e.g., SFRP2, WIF1), which in turn inhibit Wnt signaling and tumor growth." (PMID 41450947, 2025). "While dabrafenib directly inhibits BRAF activity, HT induced a broader suppression of oncogenic proteins involved in tumor-stroma crosstalk and angiogenesis, including VEGFR-2, WIF-1, ITGB5, and ERBB2/3/4." (PMID 40725203, 2025). "The top five differential genes in LumB tumours, ranked by significance, are MIS18A, WIF1, CHEK2, EMCN and CDK4." (PMID 38332687, 2024). "At the same time, Cheng established a clinical prediction model from 295 NFPA tumor samples and found that three proteins, CDKN2A/p16, WIF1, TGF-β, tumor age and volume, and two clinical features were significantly associated with the recurrence of NFPA." (PMID 37780610, 2023). "In a recent study, three protein molecules―including p16, Wif1 and TGF-β―were identified and combined with age and gross tumor volume to build a model for predicting tumor regrowth." (PMID 37763643, 2023). "Later, the same team also identified that WIF-1, a WNT antagonist belonging to the secreted frizzled-related protein (sFRP) class, functions as a tumor suppressor in RCC cells." (PMID 36910160, 2023). "The top downregulated genes [WIF1, DACT2, ID4, TP63, SOX10] in tumours in our transcriptomic profile were regulators of Wnt signalling, cell differentiation and morphogenesis and acted as inhibitors of tumour growth in BC31–34." (PMID 34997107, 2022). "EBV miRNAs attack host mRNAs and some target carcinogenesis genes. miR-BART19-3p targets WIF1, a gene important in CRC. miR-BART1 targets PSAT1, a gene promoting the replication and proliferation of tumor cells." (PMID 35174040, 2022). "miR-BART19-3p (miRNAs) is shown to attack WIF1 (host mRNAs), which is an important colon cancer gene, while miR-BART1 (miRNAs) attacks PSAT1 (host mRNAs), a tumor cell promoting gene." (PMID 35174040, 2022). "In concordance with the cell lines, SOSTDC1 and WIF1 were completely methylated but, DACT2 was hemi-methylated in tumours." (PMID 34997107, 2022). "ALKBH5 inhibits tumor motility and stemness by demethylating TIMP3, LncRNA NEAT1, WIF1, and LncRNA KCNK15-AS1." (PMID 33428593, 2021).